VARS2 (valyl-tRNA synthetase 2, mitochondrial)
Description:
Catalyzes the attachment of valine to tRNA(Val) in a two-step reaction: valine is first activated by ATP to form Val-AMP and then transferred to the acceptor end of tRNA(Val).
Synonyms: ValRS; KIAA1885; VARS2L; VARSL; DKFZP434L1435; G7a; COXPD20
Tractability: PROTAC: ubiquitination databases record sites on it; its protein half-life has been measured.
Gene: Protein-coding gene on chromosome 6 (30,914,205 to 30,926,484, forward strand). Ensembl gene ENSG00000137411.
Subcellular location: Mitochondrion
Subcellular location (Human Protein Atlas): Mitochondria
Pathways (Reactome):
Metabolism of proteins: Mitochondrial tRNA aminoacylation
Gene Ontology:
Molecular function: protein binding; valine-tRNA ligase activity; aminoacyl-tRNA deacylase activity; aminoacyl-tRNA ligase activity; ATP binding; nucleotide binding
Biological process: valyl-tRNA aminoacylation; aminoacyl-tRNA metabolism involved in translational fidelity; tRNA aminoacylation for protein translation
Cellular component: mitochondrion; cytosol
Genetic constraint (gnomAD): Loss-of-function variants: 103 observed, 150.59 expected, observed/expected ratio (o/e) 0.68, 90% interval 0.58 to 0.81. The upper end of that interval is the gene's LOEUF score, 0.81, which puts it in group 3 of 6, group 1 being the genes least tolerant of losing a copy. Missense variants: 1,149 observed, 1,340.1 expected, observed/expected ratio (o/e) 0.86, 90% interval 0.82 to 0.9. Synonymous variants: 481 observed, 536.31 expected, observed/expected ratio (o/e) 0.9, 90% interval 0.83 to 0.97.
Gene-disease validity (ClinGen):
ClinGen rates the evidence that VARS2 causes each of these diseases.
mitochondrial disease (autosomal recessive): Definitive.
Homologues: Orthologues: chimpanzee VARS2 (99% identical), macaque VARS2 (97% identical), pig VARS2 (89% identical), guinea pig VARS2 (84% identical), mouse Vars2 (84% identical), rat Vars2 (83% identical), dog VARS2 (81% identical), tropical clawed frog vars2 (52% identical), zebrafish vars2 (50% identical). Paralogues in human: VARS1 (49% identical), IARS1 (21% identical), IARS2 (21% identical), LARS1 (17% identical), LARS2 (16% identical), MARS1 (13% identical), MARS2 (11% identical).
Diseases named in the same sentence as VARS2 in open-access papers:
VARS2 is named in the same sentence as 42 diseases in open-access papers, as found by Europe PMC text mining. Sharing a sentence is not in itself a finding about the gene and the disease. The quoted sentences say what the papers report.
epilepsy (6 papers, 2014 to 2025). A brain disorder characterized by episodes of abnormally increased neuronal discharge resulting in transient episodes of sensory or motor neurological dysfunction, or psychic dysfunction. "Mitochondrial abnormalities are evident in BD and other psychiatric illnesses, and loss-of-function mutations in VARS2 have been previously associated with mitochondrial encephalopathies, epilepsy, and schizophrenia." (PMID 35922419, 2022).
mitochondrial encephalopathies (4 papers, 2014 to 2023). "Bi-allelic variants of VARS2, a nuclear gene encoding for valyl-tRNA (Val-tRNA) synthetase, are associated to several forms of mitochondrial encephalopathies or cardiomyoencephalopathies." (PMID 31064326, 2019). "Rare bi-allelic variants in VARS2 have been associated with mitochondrial encephalopathies or cardiomyoencephalopathies in 13 families with 17 affected individuals worldwide." (PMID 31064326, 2019). "VARS2 is a mitochondrial gene whose mutation is linked to mitochondrial encephalopathies." (PMID 37100811, 2023). "Our study reports the first mutations in the VARS2 and TARS2 genes, which encode two mitochondrial aminoacyl-tRNA synthetases, as causes of clinically distinct, early-onset mitochondrial encephalopathies." (PMID 24827421, 2014).
breast carcinoma (3 papers, 2015 to 2024). "A germline variant in VARS2 has been reported to be a prognostic marker, associated with survival, in early breast cancer patients." (PMID 25950620, 2015).
mitochondrial encephalomyopathies (3 papers, 2014 to 2023). "The detailed description of this cohort further delineates our understanding of the clinical presentation associated with pathogenic VARS2 variants and we recommend that this gene should be considered in early‐onset mitochondrial encephalomyopathies or encephalocardiomyopathies." (PMID 29314548, 2018). "The series of patients described here, reinforces previous findings and further delineates the range of clinical observations caused by mutations in VARS2, which should be investigated in early‐onset mitochondrial encephalomyopathies or encephalocardiomyopathies." (PMID 29314548, 2018).
cardiomyopathy (2 papers, 2019 to 2021). A disease of the heart muscle or myocardium proper. "Recently, several mutations in VARS2 gene were associated with clinical features such as hypotonia, psychomotor delay, encephalopathy, cardiomyopathy, hyperlactatemia, but the correlation between genotype and phenotype remains unclear." (PMID 33937156, 2021). "When considering our patient in comparison with previously reported patients with VARS2 mutations, it appears that the main phenotypic features are seizures, various degrees of developmental delay, facial dysmorphism, brain atrophy, and cardiomyopathy." (PMID 31623496, 2019).
diabetic retinopathy (2 papers, 2024). "Valyl tRNA aminoacylation emerged as a potential pathway associated with diabetic retinopathy; the altered expression of VARS2, a gene that encodes mitochondrial aminoacyl-tRNA synthetase, may suggest dysfunction within the mitochondria." (PMID 38791494, 2024).
hypertrophic cardiomyopathy (2 papers, 2018 to 2021). A condition in which the myocardium is hypertrophied without an obvious cause. "In the present paper we describe a compound heterozygous case with a recurrent c.1168G>A (p.Ala390Thr) and a novel missense variant c.2758T>C (p.Tyr920His) in the VARS2 gene causing isolated hypertrophic cardiomyopathy, hyperlactatemia, and pulmonary hypertension leading to early death." (PMID 33937156, 2021).
lung carcinoma (2 papers, 2023 to 2024). "For lung cancer, one SD increase of VARS2 methylation was associated with more than 20% higher risk of cancer depending on different methylation CpG sites." (PMID 36634566, 2023). "The mechanisms of VARS2 in lung cancer carcinogenesis need further evaluation by experimental studies." (PMID 36634566, 2023).
heart failure (1 paper, 2022). Inability of the heart to pump blood at an adequate rate to meet tissue metabolic requirements. "Zebrafish embryos with transient VARS2 loss-of-function showed features of heart failure as well as indications of CNS and skeletal muscle involvements." (PMID 35806332, 2022). "The VARS2 morphants showed disturbed cardiac contractility (decreased fractional shortening) and bradycardia, as well as dilated ventricles, manifest pericardial edema, and pericardial blood congestion, all hallmarks of heart failure in zebrafish." (PMID 35806332, 2022). "In this study, we found that zebrafish embryos lacking normal levels of VARS2 developed heart failure, cerebral edema, and curved backs, suggesting CNS involvement and skeletal muscle affection." (PMID 35806332, 2022).
ischemic cardiomyopathy (1 paper, 2022). Ischemic cardiomyopathy is a cardiomyopathy in which a weakness in the muscle of the heart due to inadequate oxygen delivery to the myocardium with coronary artery disease being the most common cause. "Through a GWAS, we showed possible associations between mitochondrial valyl-tRNA synthetase (VARS2) dysregulations and non-ischemic cardiomyopathy." (PMID 35806332, 2022). "Considering these results and based on our previous findings, we hypothesize that VARS2 alterations may contribute to non-ischemic cardiomyopathy or influence patients’ clinical courses and outcomes; therefore, we suggest further investigation." (PMID 35806332, 2022). "Thus, we postulated that VARS2 alterations may contribute to non-ischemic cardiomyopathies or influence patients’ clinical courses and outcomes, and we aimed to investigate the possible disease mechanisms." (PMID 35806332, 2022).
leprosy (1 paper, 2016). Leprosy is a chronic infectious disease affecting primarily the skin and peripheral nervous system. "The protein interaction network analysis supported this speculation, as we found that the other mitochondrial genes (MCCD1, SDHD, SNCA, and VARS2) could interact with the reported leprosy susceptibility genes." (PMID 27876828, 2016).
psoriasis (1 paper, 2025). An autoimmune condition characterized by red, well-delineated plaques with silvery scales that are usually on the extensor surfaces and scalp. "The co-localization analysis revealed genes positively associated with the risk of psoriasis, including HLA-DOB, NOTCH4, and VARS2." (PMID 40861805, 2025).
cancer (3 papers, 2018 to 2023). A tumor composed of atypical neoplastic, often pleomorphic cells that invade other tissues. "For example, VARS is up-regulated in 10 cancer types, whereas VARS2 is only up-regulated in two cancer types." (PMID 30588513, 2018). "There are a few aaRSs that are downregulated in multiple cancer types, including HARS2 (n = 6), WARS1 (n = 4), CARS2 (n = 4), IARS1 (n = 3), RARS2 (n = 3), VARS2 (n = 3), and AIMP3/EEF1E1 (n = 3), suggesting these aaRSs may possess certain specific cancer-inhibiting roles." (PMID 33266490, 2020).
mitochondrial disease (2 papers, 2014 to 2023). "In conclusion, we identified novel mutations in two genes encoding mitochondrial aminoacyl-tRNA synthetases (VARS2 and TARS2), which have not been appreciated previously as causing mitochondrial disease, thus expanding the list of aaRS2-associated diseases." (PMID 24827421, 2014).
infection (1 paper, 2024). The state of being infected such as from the introduction of a foreign agent such as serum, vaccine, antigenic substance or organism. "However, after infection, we observed 15 genes with significant differences between the two host genotype groups (Pt-test < 0.05), including IER3, VARS2 and ZNRD1 involved in immune response, ER stress and zinc homeostasis." (PMID 39613754, 2024).
VARS2 also shares sentences with these, for which no sentence is quoted: developmental delay (2 papers); hypogonadism (2); lactic acidosis (2); metabolic acidosis (2); prostate carcinoma (2); Angelman-like syndrome (1); Brain atrophy (1); dilated cardiomyopathy (1); encephalomyopathies (1); Encephalopathy (1); endocrine disorder (1); epilepsia partialis continua (1); Epileptic encephalopathy (1); Leigh syndrome (1); leukodystrophies (1); metabolic disease (1); microcephaly (1); myocardial hypertrophy (1); ovarian carcinoma (1); ovarian failure (1); renal cell cancer (1); schizophrenia (1); sensorineural hearing loss with (1); tumor (1); type 1 diabetes mellitus (1); type 2 diabetes (1); viral infection (1).